STAT3 (signal transducer and activator of transcription 3)
Diseases named in the same sentence as STAT3 in open-access papers (continued):
Sharing a sentence is not in itself a finding about the gene and the disease.
lymphoma (continued). "And the STAT3 (rs744166), IL2 (rs2069762), IL10 (rs1800871), and PARP1 (rs907187) manifested a significant relationship with the peripheral blood counts in lymphoma patients." (PMID 37329186, 2023). "SD-36 induced proteolysis of STAT3 and pSTAT3Y705 with DC50 of 28 nM and 60 nM in SU-DHL-1 (lymphoma) and MOLM-16 (leukemia) cells, respectively." (PMID 36986673, 2023). "The signal transducer and activator of transcription 3 (STAT3), which regulates multiple oncogenic processes, has been found to be constitutively activated in lymphoma, suggesting its potential as a therapeutic target." (PMID 37686472, 2023). "The role of STAT3 activation in lymphoma has been highlighted mainly in the ABC DLBCL and EBV+DLBCL, and EBV oncoprotein LMP1 can induce STAT3 activation." (PMID 36765793, 2023). "STAT3 and STAT6 have lymphoma-promoting properties due to their activation of genes encoding for proteins such as MYC, BCL-XL and CYCLIND1." (PMID 36671496, 2023). "STAT3 shRNA inhibited proliferation and downregulated the expression of c-MYC, CCND1, and BRIC5 in vitro and in vivo in the SCC-3 lymphoma cells." (PMID 38067351, 2023). "The degrader 114 (SD-91) bound to STAT3 protein with a high affinity, and was more potent than SD-36 in inducing degradation of STAT3 in SU-DHL-1 and MOLM-16 lymphoma cells." (PMID 35680848, 2022). "STAT3 PROTAC degraders have been reported to downregulate STAT3 and showed therapeutic effects in leukemia and lymphoma cells." (PMID 35313878, 2022). "Those notions are especially significant since NF-kB, STAT3, PI3K, and AKT pathways are activated in lymphoma cells via leptin/LEPR signaling and improving bcl-2 expression." (PMID 36555171, 2022). "Deacetylation of STAT3 by the histone deacetylase HDAC3 promotes STAT3 activation in hepatocytes and lymphoma cells." (PMID 36341403, 2022). "On the basis of our previous study, the aberrant expression of Sox2 in these lymphoma cells is attributed to the constitutive activation of the NPM-ALK/STAT3 axis, and inhibition of either ALK or STAT3 led to a substantial decrease in Sox2 expression." (PMID 34287231, 2021). "Blockage of STAT3 is accompanied by decreased NK infiltration and reduced levels of IFN-γ in lymphoma." (PMID 34804058, 2021). "One promising STAT3 ASO, AZD9150, showed efficiency when systemically administered in preclinical trials for lymphoma and lung cancer (NSCLC) patients." (PMID 34440253, 2021). "AZD9150, a STAT3-inhibiting ASO, has demonstrated tumor suppressive activity in lung and lymphoma models as well as in a phase1b trial of pretreated lymphoma patients." (PMID 33804473, 2021). "Both proteins, STAT3 and STAT5B, are activated in virtually all of the alimentary lymphoma samples examined." (PMID 34680385, 2021). "We showed that STAT3 interacts with DNMT1 and HDAC1 both in CD8+ T cells and KAI3 NK cells, which is in line with previous studies showing STAT3-DNMT1-HDAC1 complex in lymphoma cells." (PMID 34075200, 2021). "Fusion of the STAT3 decoy with CpG has enabled targeting of the decoy to TLR9-expressing leukemia and lymphoma cells." (PMID 31671769, 2019). "Preclinical studies with AZD9150 in lymphoma (KARPAS299 and SUP-M2) and neuroblastoma (IMR 32) cell lines with aberrantly activated STAT3 showed a decrease in the expression of STAT3 protein and downstream signaling targets." (PMID 31671769, 2019). "As oncogenic tyrosine kinase, NPM-ALK is known to phosphorylate and activate several proteins: STAT3 as a major player in ALCL is constitutively phosphorylated by binding to NPM-ALK, and thereby contributes to lymphoma pathogenesis." (PMID 31434245, 2019).
lymphoma (continued). "IL-6-induced STAT3 or STAT5 activation is associated with the acquired resistance to PI3K inhibitors in T- and B-cell lymphoma cell lines, and co-targeting JAK/STAT3 and PI3K signaling resensitizes the lymphoma cell lines to a PI3K inhibitor." (PMID 31861597, 2019). "Another lymphoma dataset (Compagno Lymphoma Statistics) indicated that the expression levels of CD44 and STAT3 were higher in ABC than those in GCB." (PMID 29992138, 2018). "These therapies are RNA-based (not miRNA-based); they do not knockdown or overexpress miRNAs but target oncogenes such as Bcl-2 (NCT00285103) in CLL, STAT3 (NCT01563302) in DLBCL and lymphoma, and MYC (NCT02314052) in HCC." (PMID 30443251, 2018). "The CpG-STAT3dODN blocked STAT3 DNA binding and activity, thus reducing expression of downstream target genes, such as MYC and BCL2L1, in human and mouse lymphoma cells." (PMID 29433938, 2018). "The STAT3 inhibition, through the reversible decoy effect, combined with concurrent TLR9 activation seemed sufficient for the induction of the lymphoma differentiation to antigen-presenting phenotype, thereby ensuring therapeutic antitumor efficacy." (PMID 29433938, 2018). "Accordingly, the combination of THZ1 and the BH3 mimetic obatoclax improves lymphoma growth control in a primary PTCL ex vivo culture and in two STAT3-mutant PTCL xenografts, delineating a potential targeted agent-based therapeutic option for these patients." (PMID 28134252, 2017). "Signal transducers and activators of transcription 3 (STAT3), a member of the STAT protein family, is a cytoplasmic transcription factor and is aberrantly activated in several cancers such as lymphoma, breast, lung, ovarian, prostate, and liver cancers." (PMID 28635648, 2017). "Some reports have shown that STAT3 can increase the expression of the NK activating receptor NKG2D and promote NK-mediated immunosurveillance in some lymphoma models." (PMID 27148255, 2016). "In this type of lymphoma, NPM-ALK binds to, phosphorylates and activates STAT3, which has been shown to be central to the NPM-ALK—mediated tumorigenesis." (PMID 24995504, 2014). "Numerous studies have demonstrated that constitutively activated STAT factors, particularly STAT3 and STAT5, have been found in a wide variety of human tumors, including blood malignancies (leukemias, lymphomas)." (PMID 22151181, 2011). "As LMP1 was reported to autoactivate its own expression in EBV-infected HeLa cells by increasing STAT3 expression, the ability of Myc to block LMP1 expression in BL-like lymphomas could potentially be due to Myc inhibition of STAT3 and/or Src gene expression." (PMID 38620028, 2024). "Pre-clinically, we found that blocking the β2-AR signaling, STAT-3 signaling or ATP and Itaconate metabolites results in enhancement of doxorubicin chemotherapy, marked by reduced tumor growth and increased survival in the EL4 murine lymphoma model." (PMID 38555305, 2024). "Also, chronic inflammation promotes an increase in chromosomal aberrations that enhance the activity of STAT3 and STAT5, or alterations leading to the progression of the lymphoma, such as TP3, MYC, and PTEN." (PMID 38435536, 2024). "The expression level of total Src protein, and tyrosine 705-phosphorylated STAT3 protein, is also decreased in the Myc-expressing lymphomas although the level of total STAT3 protein is not consistently different." (PMID 38620028, 2024). "There was no previous study pertaining to the expression of STAT-3 protein in T-lymphoblastic leukemia/lymphoma for comparison." (PMID 37175040, 2023). "Apart from DLBCL, there was little difference between other cases of lymphoma subtypes that did not express STAT-3 and those that did." (PMID 37175040, 2023). "Transplantation of the lymphoma cells lacking STAT3 into mice harboring NK cells results in accelerated tumor growth, but the difference is lost in immune-deficient mice." (PMID 35865518, 2022).
lymphoma (continued). "Notably, PTGDS inhibition displayed excellent anti-lymphoma effects in vitro and in vivo study, through MYH9-mediated regulation of Wnt–β-catenin–STAT3 signaling." (PMID 34743203, 2022). "We show that T cell activation does not significantly upregulate STAT3 expression in T cells of lymphoma patients as compared to healthy controls." (PMID 36359267, 2022). "Interestingly, we found that STAT3 binds to super-enhancers that regulate high expression of Bcl-xL in both ALK+ and ALK− ALCL lymphoma cell lines." (PMID 36045346, 2022). "Several studies indicated that STAT3, an important transcription factor in tumors, was downstream of the Wnt pathway and our previous research found that STAT3 inhibitor WP1066 exhibited anti-tumor effects in lymphoma." (PMID 34743203, 2022). "Recent evidence shows that some AIDS-related T cell lymphomas have clonal integration of HIV proviruses in the first intron of STAT3, a gene central to lymphocyte growth signaling, and one often mutated in non-AIDS lymphomas." (PMID 34696507, 2021). "Phosphorylation of Tyr-705 in the SH2 domain is well characterized as an early event for STAT3 activation, which is mediated by JAKs and nonreceptor kinases, such as Src and Abl autoimmune diseasesions in lymphoma cells." (PMID 31861597, 2019). "As performed similarly in A20 lymphoma, three IT injections of CpG(B)-STAT3dODN (1 mg/kg), but not CpG(B)-scrODN or PBS, inhibited STAT3 DNA binding in human OCI-Ly3 lymphoma, as assessed using the EMSA." (PMID 29433938, 2018). "Similarly, the small-molecule STX-0119 was able to inhibit STAT3 dimerization and suppress human lymphoma SCC3 cell growth, through apoptosis and downregulation of known STAT3 targets." (PMID 30283459, 2018). "The phosphorylation of STAT3 by integrin-activated Syk was only recently found in acute myeloid leukemia cells and T-lymphoma cells, but not in activated B lymphoid cells." (PMID 26848618, 2016). "Downregulation of the phosphorylated form of NPM-ALK by ASP3026 was associated with a remarkable reduction in the phosphorylation levels of IGF-IR, STAT3, AKT, and JNK proteins, which are established targets of NPM-ALK signaling that contribute significantly to the survival of this lymphoma." (PMID 25026277, 2014). "Here we compared the immunogenicity of Primary Effusion Lymphoma (PEL) cell death induced by anticancer drug Bortezomib (Velcade) and Tyrphostin AG 490, a Janus Activated Kinase 2/signal trasducer and activator of transcription-3 (JAK2/STAT3) inhibitor." (PMID 22412839, 2012). "STAT3 signalling is also likely enhanced in this lymphoma due to the fact that ALK+ ALCL cell lines do not express the STAT3 inhibitor, PIAS3." (PMID 22852078, 2012). "Considering that there is a certain dependence of both NF-κB and STAT3 on PI3K signaling, and that NF-κB and STAT3 are physically located in the same molecular complex, these results suggest that PI3K, NF-κB and STAT3 converge in Myc-driven lymphoma." (PMID 20433747, 2010). "Here, we constructed an anti-CD19-N-(4-carboxycyclohexylmethyl) maleimide N-hydroxysuccinimide ester (SMCC)-protamine (CSP)-STAT3 small interfering RNA (siRNA) conjugate and demonstrated that the CSP-STAT3 siRNA conjugate could specifically bind to normal B cells and A20 lymphoma cells in vitro." (PMID 37686472, 2023). "STAT3 dephosphorylation could be detrimental to lymphoma cells since we and other demonstrated that silencing STAT3 using specific shRNAs or degrading STAT3 with the PROTAC degraders, a new class of compounds, induce lymphoma cell-cycle arrest and and/or apoptosis." (PMID 36698412, 2022). "We also evaluated in the two cell lines the activation of STAT3 and NF-κB pathways by western blot and found that OPL241 line shows the strongest expression of phospho- and total p65, ph-STAT3, and BCL2, in agreement with the high histological grade of the original lymphomas." (PMID 36503430, 2022).
lymphoma (continued). "Cre-mediated deletion of STAT3 in Eμ-myc B cells did not alter the development of lymphomas." (PMID 33651821, 2021). "Our findings mechanistically link constitutively active STAT3 to HR impairment in EBV-transformed cells and support the idea that EBV-lymphomas including LPD, BL, and certain DLBCL (Diffuse Large B-Cell Lymphomas) may be susceptible to synthetic lethal approaches including PARP inhibition." (PMID 33002095, 2020). "In a previous study by Liu, STAT3 was co-localized with S1PR1 in the tumor cells of a few ABC DLBCL tissues, and the inhibition of S1PR1 with FTY720 or S1PR1 shRNA successfully suppressed STAT3 activity and tumor cell growth in vitro and in an in vivo murine lymphoma model." (PMID 25472725, 2014). "Specifically, we have demonstrated that the K-Ras pathway and its down-stream effector Stat3 are correlated with the ability of K-rasG12D or MYC to initiate lung tumorigenesis and that down regulation of the K-Ras/Stat pathway is strongly correlated with lung tumor and lymphoma regression." (PMID 18461184, 2008). "However, in the lymphomas, the proviruses would be expected to induce the expression of the full length STAT3 protein and in the in vitro experiments, most, but not all of the proviruses would be expected to induce the expression of a slightly truncated form of STAT3." (PMID 34696507, 2021). "However, the potential of STAT3 to promote invasion in various cancers may well relate to the massive tissue invasion by HVS-lymphoma cells, which is not reflected in the cell culture system." (PMID 22385615, 2012). "In summary, STAT3 and STAT5B, but not STAT5A, are relevant therapeutic targets in the treatment of lymphomas." (PMID 31963765, 2020). "Lymphomas in this model lacking Tyk2 have reduced STAT1 and STAT3 phosphorylation and reduced expression of Mcl1, a pro-survival member of the BCL2 family." (PMID 30131584, 2019). "Not surprisingly, activated STAT3 alone can also increase PD-L1 expression by directly acting on the promoter of PD-L1 in HNSCC and lymphoma cells, and STAT3 silencing leads to the downregulation of PD-L1 in ALK-negative ALCL cells and KRAS-mutant NSCLC cells." (PMID 31258527, 2019). "Targeting STAT3 in the bone marrow did not have any effect on NK cell development in vivo; overall numbers and cytotoxic activity toward standard YAC-1 lymphoma targets in the knockout mice were comparable to WT animals." (PMID 27148255, 2016). "Given the importance of STAT3 transcriptional activity in ALK+ ALCL, it is not surprising that many mechanisms contribute to the activation of STAT3 in this lymphoma." (PMID 22852078, 2012). "STAT3 has been identified as XPO1 cargo in breast cancer, and although it has not yet been validated in lymphoma, its importance in immune cell maturation and activation and presence of a bona fide XPO1 binding NES suggests that it is most likely an XPO1 cargo molecule in NHL." (PMID 36671496, 2023). "Thus, miR21-mediated p-STAT3 phosphorylation was necessary for the induction of ICOS expression on Treg cells, independent of Bcl-2 expression of lymphoma cells." (PMID 28637496, 2017). "Interestingly, in B-Non Hodgkin’s lymphomas (B-NHL) there appears to be a Lyn/Cbp/STAT3 signaling complex, not present in ALK+ T lymphoma or Hodgkin-derived lymphoma cells, that doesn’t contain the Lyn inactivating Csk kinase and promotes survival signals in these lymphomas." (PMID 22805580, 2012).
leukemia (242 papers, 2004 to 2026). A malignant (clonal) hematologic disorder, involving hematopoietic stem cells and characterized by the presence of primitive or atypical myeloid or lymphoid cells in the bone marrow and the blood. "Mutations in STAT3 also influence tumor proliferation; inhibitors of STAT3 can alter the susceptibility of leukemia cells to apoptosis, while normal cells remain unaffected." (PMID 40143362, 2025). "In the cohort of T-LGL leukemia with SS, STAT3 mutations were found in 12 (57%) patients: in 1 patient with pSS and in 11 patients with sSS." (PMID 36362126, 2022). "In previous studies, STAT3 somatic mutation allele fractions in T-LGL leukemia have been typically >15%, in Felty syndrome 1–9%, in myelodysplastic syndrome 0.6–13%, and in aplastic anemia on average 4.5%." (PMID 36441748, 2022). "PM2.5 can lead to the excessive production of ROS by activating NADPH oxidase to enhance the expression of inflammatory mediators in leukemia cells through the NF-κB p65 and p-STAT3 pathways, while ROS can even cause oxidative stress in lung epithelial cells." (PMID 36544791, 2022). "Whole exome sequencing in a large T-LGL leukemia cohort identified additional genes with recurrent somatic variants as well as frequent co-mutations of chromatin modifying genes in STAT3-mutant T-LGLs." (PMID 35646651, 2022). "All in all, the main lesson to learn from TGL leukemia is that STAT3 signaling is associated with a significant survival advantage for T cells, even in the absence of other oncogenic mutations." (PMID 35270020, 2022). "A 2019 retrospective study of one of the largest LGL leukemia cohorts to date revealed that STAT3 mutations were associated with low hemoglobin and lower overall survival, as well as severe neutropenia." (PMID 35646651, 2022). "It has recently been shown that JAK2 inhibitor, AG490, causes the dephosphorylation of STAT3 and enhances cytotoxic activity of conventional chemotherapeutics in leukemia cells." (PMID 33807148, 2021). "Inhibition of STAT3 is further associated with decreased survival rate of leukemia cells, increased apoptosis and differentiation, implying that the STAT3 pathway plays an imperative role in AML cells." (PMID 33893245, 2021). "Upregulation of signal transducer and activator of transcription 3 (STAT3) and NF-κB are two fundamental transcription factors that are associated with many types of cancer, including leukaemia." (PMID 33802972, 2021). "Our previous studies demonstrated that CAMKIIγ can activate multiple leukemia-associated signaling networks by NF-κB, β-catenin and Stat3 pathways, which are essential for survival and self-renewal of leukemia stem cells (LSC)." (PMID 32658867, 2020). "In CD8+ TCRαβ+ T-LGL leukemia altered signaling through STATs has been implicated in the leukemogenesis, based on the frequent occurrence in mutations in the STAT3 and/or STAT5b genes." (PMID 28407008, 2017). "Constitutive STAT5 activation is also observed in the majority of leukemias and many solid tumors, encoding by Stat5a and Stat5b genes on human chromosome 17 in a locus that also contains the Stat3 gene." (PMID 28422733, 2017). "This persistent activation of STAT3 is a hallmark of leukemia and contributes to tumor progression." (PMID 40943567, 2025). "One possibility for the co-occurrence of RA and T-LGL leukemia is that the clonal expansion of CD8+ T cells in RA may result in the acquisition of STAT3 and other somatic mutations, T cell transformation, and the development of leukemia." (PMID 35646651, 2022). "The SH2 domain of STAT3 has been found to be mutated in patients with large granular lymphocytic leukemia as well as other types of leukemias, thus indicating that anomalous STAT3 signaling may be underlying the pathogenesis of these diseases." (PMID 30217007, 2018). "Finally, the LGL Leukemia Registry enabled us to study large groups of the most common STAT3 mutations to discern whether different mutations affect blood counts." (PMID 32710512, 2020).